CIP2A (cellular inhibitor of PP2A)
Diseases named in the same sentence as CIP2A in open-access papers (continued):
Sharing a sentence is not in itself a finding about the gene and the disease.
cognitive decline (1 paper, 2022). "The bioinformatics data together indicate that upregulation of SERPINA1, VCP, PRNP, CIP2A, HSPA9, and UQCRC2 and downregulation of IGFBP3, CRHBP, PEPD, and GUSB were correlated to cognitive decline in T2DM patients." (PMID 36506101, 2022). "Further studies by ELISA and Peterson’s analyses validated that the upregulation of CIP2A, PRNP, and CRHBP and downregulation of VCP were indeed correlated to cognitive decline in T2DM patients." (PMID 36506101, 2022).
diabetes (1 paper, 2016). "The expression of CIP2A was found to be correlated with TNM stage, but not correlated with age, gender, tumor location, smoking status, alcohol consumption, diabetes, high blood pressure, BMI, tumor size, lymph node metastasis or distant metastases." (PMID 26894380, 2016).
dysplasia (1 paper, 2011). A usually neoplastic transformation of the cell, associated with altered architectural tissue patterns. "As a trend, cytoplasmic CIP2A expression was higher in severe epithelial dysplasia than in mild dysplasia, compared with nuclear CIP2A, which was low in severe dysplasia but was expressed to a greater extent in lesions with mild dysplasia." (PMID 21610708, 2011).
embryonal carcinoma (1 paper, 2015). A non-seminomatous malignant germ cell tumor characterized by the presence of large germ cells with abundant cytoplasm resembling epithelial cells, geographic necrosis, high mitotic activity, and pseudoglandular and pseudopapillary structures formation. "To further study the possible link between CIP2A and Oct4 we used two different TC cell lines derived from either seminoma (Tcam2) or embryonal carcinoma (Tera1)." (PMID 25474139, 2015).
female infertility (1 paper, 2025). Diminished or absent ability of a female to achieve conception. "Consistent with our findings, recent studies have shown that CIP2A knockdown causes dispersed chromosomes in human oocytes, and CIP2A loss-of-function mutation is associated with female infertility with early embryonic arrest and fragmentation." (PMID 39657788, 2025).
hepatoblastoma (1 paper, 2019). Hepatoblastoma (HB) is a malignant hepatic tumor and is the most common pediatric liver cancer. "We have demonstrated that FTY720 activates PP2A in hepatoblastoma, but does not do so via inhibition of the endogenous inhibitors, CIP2A and I2PP2A, as previously observed in other cancers." (PMID 30969990, 2019).
Infertility (1 paper, 2025). "While reversing CIP2A inhibition restored sperm production, these findings raise concerns about the potential for infertility in men receiving CIP2A inhibitors, especially those planning to have children." (PMID 41155727, 2025).
invasive carcinoma (1 paper, 2011). A carcinoma that is not confined to the epithelium, and has spread to the surrounding stroma. "In invasive carcinomas, cytoplasmic CIP2A protein expression was either low or high." (PMID 21610708, 2011).
malignant mesothelioma (1 paper, 2025). A malignant neoplasm of the pleura or peritoneum, arising from mesothelial cells. "One previous in silico analysis showed that the concurrent expression of ANP32E and CIP2A was a poor prognostic factor in patients with malignant mesothelioma." (PMID 39852534, 2025).
metastatic colorectal cancer (1 paper, 2015). "CIP2A expression was an independent prognostic marker in patients with wild-type KRAS metastatic colorectal cancer after colorectal liver metastasectomy (relative risk = 1.873, P = 0.019)." (PMID 25896895, 2015). "In our analysis, the value of CIP2A as a prognostic marker was limited to patients with wild-type KRAS metastatic colorectal cancer after colorectal liver metastasectomy." (PMID 25896895, 2015). "CIP2A is an independent prognostic marker in patients with wild-type KRAS metastatic colorectal cancer after colorectal liver metastasectomy." (PMID 25896895, 2015). "After adjusting for other confounding factors, we found that CIP2A acts as an independent prognostic marker in patients with wild-type KRAS metastatic colorectal cancer after colorectal liver metastasectomy." (PMID 25896895, 2015). "CIP2A is an independent prognostic marker in patients with metastatic colorectal cancer exhibiting wild-type KRAS after colorectal liver metastasectomy." (PMID 25896895, 2015). "We found that CIP2A only acts as an independent prognostic marker in patients with wild-type KRAS metastatic colorectal cancer after colorectal liver metastasectomy." (PMID 25896895, 2015). "Therefore, the interplay between EGFR signaling and CIP2A in metastatic colorectal cancer warrants further investigation." (PMID 25896895, 2015).
myelofibrosis (1 paper, 2017). A partial or complete replacement of the bone marrow stroma by fibrous tissue. "The relevance of this observation was strengthened by the analysis of CIP2A mRNA levels in granulocytes from 14 patients with myelofibrosis who had received RAD001 in a phase II clinical trial." (PMID 29228564, 2017). "The levels of CIP2A were found increased in cells harboring the JAK2V617F mutation, and we provide evidence of a correlation between clinical responses and the extent of CIP2A downregulation in myelofibrosis patients receiving the mTOR inhibitor RAD001 in a phase II clinical trial." (PMID 29228564, 2017).
myeloid leukemia (1 paper, 2022). A clonal proliferation of myeloid cells and their precursors in the bone marrow, peripheral blood, and spleen. "Previously it was shown that the expression levels of cellular inhibitors of PP2A (CIP2A) and novel splice variants of CIP2A are associated with sensitivity to imatinib in myeloid leukemia." (PMID 36115852, 2022).
nodular melanomas (1 paper, 2015). "For this reason we have examined CIP2A protein expression in a panel of superficial spreading (SSM) and nodular melanomas (NM) and assessed the relationship to clinical outcome." (PMID 25663244, 2015).
orchitis (1 paper, 2021). Inflammation of one or both testes due to viral or bacterial infections. "Altogether, these results highlighted the association between OCT4 and CIP2A in LPS-induced testicular cells during orchitis." (PMID 34513828, 2021). "Taken together, these results warrant the further investigation of OCT4 and CIP2A as two potential therapeutic targets of orchitis." (PMID 34513828, 2021). "This study was conducted to ascertain whether OCT4 and CIP2A play important roles in inflammation, cell death, and redox equilibrium during orchitis." (PMID 34513828, 2021). "Intriguingly, inhibition of CIP2A by TD-19 administration abolished the effect of OCT4 overexpression on inflammation, apoptosis, and antioxidant response in LPS-treated testicular cells, suggesting an anti-inflammation effect of CIP2A in orchitis." (PMID 34513828, 2021). "Inhibition of CIP2A expression in LPS-treated testicular cells repressed the activation of the Keap1-Nrf2 pathway, increased ROS generation, and inhibited antioxidant levels, thus, confirming the protective effects of OCT4 and CIP2A against oxidative stress in LPS-induced orchitis." (PMID 34513828, 2021).
osteosarcoma (1 paper, 2014). A usually aggressive malignant bone-forming mesenchymal neoplasm, predominantly affecting adolescents and young adults. "Knockdown of CIP2A expression significantly reduced osteosarcoma cell proliferation and invasion, with decreased c-MYC expression and p-AKT expression." (PMID 25015035, 2014). "CIP2A has been identified as a critical oncoprotein involved in cell proliferation and invasion, which could serve as a therapeutic target in osteosarcoma." (PMID 25015035, 2014).
ovarian adenocarcinoma (1 paper, 2011). An adenocarcinoma that arises from the ovary. "The cellular sublocalisation of CIP2A protein was studied in the ovarian adenocarcinoma cell lines CaOV3, OVCAR-3, and OV-4." (PMID 21897396, 2011).
prostatic adenocarcinoma (1 paper, 2010). "Expression of the CIP2A protein was studied using immunohistochemistry and archival tissue specimens of prostate adenocarcinoma (n = 59) and BPH (n = 20)." (PMID 20964854, 2010). "In conclusion, these results suggest that expression of the CIP2A protein is increased in the epithelial cell compartments of prostatic adenocarcinoma." (PMID 20964854, 2010).
pulmonary diseases (1 paper, 2025). "CIP2A upregulation is linked to several signaling cascades associated with pulmonary diseases, such as excessive proliferation, inflammation, EMT, fibroblast activation, and collagen deposition." (PMID 41155727, 2025). "Understanding these mechanisms is crucial for developing targeted therapies aimed at modulating CIP2A activity in pulmonary diseases." (PMID 41155727, 2025). "The previous sections explored the potential benefits of targeting CIP2A, particularly in the context of pulmonary diseases." (PMID 41155727, 2025). "This review outlines the possible impact of CIP2A-mediated signaling in pulmonary diseases, the processes that regulate CIP2A responses, CIP2A-dependent pathways, and potential therapeutic strategies targeting CIP2A." (PMID 41155727, 2025). "The clinical tolerability of CIP2A inhibitors is a critical consideration when evaluating their use in lung disease treatment." (PMID 41155727, 2025). "The development of specific inhibitors of CIP2A that selectively target its expression or protein stability could improve our understanding of CIP2A’s function in pulmonary diseases." (PMID 41155727, 2025). "Before delving into the function and signaling responses of CIP2A, it is important to outline the relevance of the pulmonary diseases, in which CIP2A could contribute to initiation or progression." (PMID 41155727, 2025). "Therefore, pulmonary diseases are a major obstacle, and determining new targets, such as CIP2A, is critical in identifying future therapies." (PMID 41155727, 2025). "However, in recent years several research studies suggest that CIP2A may also play a role in pulmonary diseases, particularly in conditions driven by inflammation, fibrosis, and tumorigenesis." (PMID 41155727, 2025). "Therefore, CIP2A may play a role in other pulmonary diseases beyond what is outlined here." (PMID 41155727, 2025).
rectal adenocarcinoma (1 paper, 2018). "We have investigated CIP2A protein levels in rectal adenocarcinomas from patients receiving either short‐ or long‐course preoperative (chemo)radiotherapy or no treatment before surgery." (PMID 29441695, 2018). "We have evaluated CIP2A protein expression levels in relation to tumor regression after preoperative (C)RT and survival of rectal adenocarcinoma patients." (PMID 29441695, 2018).
rheumatoid arthritis (1 paper, 2011). A chronic, systemic autoimmune disorder characterized by inflammation in the synovial membranes and articular surfaces. "More recently, CIP2A expression has been found to be associated with synovial hyperplasia and invasive function of fibroblast-like synoviocytes in rheumatoid arthritis." (PMID 22075943, 2011).
T-cell leukemia (1 paper, 2011). A malignant disease of the T-lymphocytes in the bone marrow, thymus, and/or blood. "In addition, the results of a recent study, demonstrating binding of ETS1 on CIP2A promoter in Jurkat T-cell leukemia strongly supports our main conclusion that ETS1 specifically is involved in positive regulation of CIP2A." (PMID 21445343, 2011).
thyroid (1 paper, 2022). "Tingting Chao and co-workers revealed that KIAA1524, also known as CIP2A, was more expressed in PTC than in thyroid non-tumor tissues and benign tumor tissues." (PMID 36530988, 2022).
cancer (139 papers, 2010 to 2026). A tumor composed of atypical neoplastic, often pleomorphic cells that invade other tissues. "Recent studies identified CIP2A as a potential synthetic-lethal target in BRCA-mutated cancers, indicating its role in HR-deficient cells." (PMID 39657788, 2025). "PP2A expression is associated with downregulation of the Akt pathway, where CIP2A overexpression is associated with Akt upregulation and cancer proliferation." (PMID 41155727, 2025). "Acknowledging the functional importance of high CIP2A protein expression in human cancers, we explored the potential impact of cancer-derived CIP2A head domain mutations on the protein expression." (PMID 36854761, 2023). "Recently, the effects of SET and CIP2A proteins on the mutations and drug resistance of cancer cells have provided new insights into cancer therapy." (PMID 37097392, 2023). "The upregulation of the PP2A inhibitor CIP2A is associated with increased cancer cell proliferation and the upregulation of multiple downstream mediators, including JNK, MKK4, ATF2, and c-Jun." (PMID 37763671, 2023). "CIP2A/p90 was overexpressed in 65%–90% of tissues in almost all human cancers, and this has been associated with poor survival." (PMID 36911405, 2023). "Our results delineate the unique role of the PP2A inhibitor proteins in tumorigenesis, and potentially explain why SET and CIP2A are frequently overexpressed concomitantly with mutations in ERK-activating oncogenes in human cancers." (PMID 36463234, 2022). "Over 150 clinical papers have subsequently confirmed that high CIP2A levels are associated with adverse histology and/or poor response to treatment in over 20 different cancer histologies, including AML." (PMID 33947031, 2021). "Both OCT4 and CIP2A, which are highly expressed in human cancers, are associated with low survival and poor resistance after patients receive DNA-damaging treatments." (PMID 34513828, 2021). "CIP-2A identification in HPV-associated cancers implies the clinical prominence of this protein as a cancer biomarker and a potential therapeutic target." (PMID 31001477, 2019). "Since endogenous inhibitors of PP2A are physiological proteins found in various human cells, the overexpression of SET and CIP2A plays a vital part in causing cancer in humans." (PMID 30341686, 2018). "Overexpression of cancerous inhibitor of protein phosphatase 2A (CIP2A) has been demonstrated in several cancers and is frequently associated with reduced survival." (PMID 29441695, 2018). "Cancerous inhibitor of protein phosphatase 2A (CIP2A, also known as p90 tumor‐associated antigen or KIAA1524) has been reported to be overexpressed in cancer and is an emerging predictor for prognosis in various cancer types including CRC." (PMID 30063110, 2018). "Identification of CIP2A as an intracellular target of lapatinib also supports CIP2A as a novel target in cancer therapy, as it is implicated in celastrol, erlotinib, and afatinib-induced anti-cancer effects." (PMID 28938602, 2017). "Clinical data further indicate that CIP2A overexpression is frequently detected in breast and other types of cancers, which are associated with poor clinical outcomes." (PMID 28938602, 2017). "The discovery of CIP2A as a regulator in HPV-associated cancer is of clinical importance for cancer diagnosis and potential therapeutic targeting." (PMID 25650660, 2015). "Increased phosphorylation of transcription factor MYC at serine 62 is a hallmark of CIP2A function in cancer cells." (PMID 25474139, 2015). "The first time deregulated CIP2A expression was linked to blood cancer development was through the discovery of a chromosomal translocation, resulting in an MLL-KIAA1524 fusion protein in an isolated case of infant AML." (PMID 25566494, 2014). "The robust expression of CIP2A is a causative factor of many types of human cancer and is associated with resistance to chemotherapy." (PMID 25334061, 2014).
cancer (continued). "Previous studies have indicated that CIP2A is an oncoprotein to promote cancer cell proliferation through inhibition of c-myc associated PP2A phosphatase activity." (PMID 25109354, 2014). "In order to identify promoter regions functionally implicated in regulation of CIP2A expression in cancer cells, we created altogether 10 promoter deletion reporter constructs." (PMID 21445343, 2011). "High expression of CIP2A is associated with a high incidence of cancer and a poor prognosis." (PMID 41362702, 2025). "Our previous studies indicated anti-cancer effect of celastrol was associated with CIP2A reduction." (PMID 37470692, 2023). "The cancer relevance of the results is demonstrated by the abrogation of tumour growth of TNBC cells by single point mutation of the N-terminal B56α interaction domain of CIP2A." (PMID 36854761, 2023). "To test this hypothesis, we first determined whether overexpression of SET or/and CIP2A co-occurred with mutations of ERK-activating oncogenes in human cancers." (PMID 36463234, 2022). "The mechanisms of CIP2A activation and overexpression in cancer cells have been investigated by several studies, in which some pathways were found to be associated with development of cancer, such as PI3K/mTOR and MAPK/ERK signaling pathway." (PMID 32321509, 2020). "Based on the important role of CIP2A in regulating the numerous signaling pathways, it is easy to explain why CIP2A protein is associated with the prognosis of cancer, which may be served as a potential cancer therapy target." (PMID 30044786, 2018). "In addition to the role of CIP2A in promoting cellular transformation and cancer aggressiveness, CIP2A is also associated with a high tumour grade (for a review see Ref.11)." (PMID 29893470, 2018). "This is most likely biologically meaningful as we observed a synergistic survival effect between CIP2A and RAS expression as well as KRAS activating mutations in TCGA pan-cancer data set, and synergistic relationship between CIP2A and KRAS depletion in colony growth assays." (PMID 26278961, 2015). "CIP2A was initially identified as a cancer-associated autoantigen in gastric and liver cancer." (PMID 26560124, 2015). "Moreover, CIP2A overexpression has been associated with tumor grade and poor prognosis in many cancers." (PMID 25650660, 2015). "We conclude from current evidence that CIP2A is an important molecule associated with cancer cell survival and could be a potential anticancer target in many malignant diseases." (PMID 25228280, 2014). "The overexpression of CIP2A in cancer cells is associated with increased cell proliferation." (PMID 25109354, 2014). "CIP2A was not only associated with the proliferation of the tumor cells or the progression of the disease, it was also found to be associated with the chromosomal translocation in these cancers." (PMID 25015035, 2014). "Despite a relatively low number of patients in our study, and therefore a relatively low number of cancer-related deaths in subgroup analyses, we could demonstrate a significant correlation of CIP2A levels with tumour-associated survival." (PMID 24098375, 2013). "Recent identification of CIP2A as a cancer-associated protein that inhibits PP2A activity towards MYC shed light on the previously unanswered question of how PP2A tumor suppressor activity is regulated in cancer cells." (PMID 22461891, 2012). "Consequently, these findings further emphasise the mitotic CIP2A-TOPBP1 axis as a promising therapeutic target in BRCA1/2-deficient cancers and those with elevated DNA replication stress, while highlighting actionable avenues for anti-cancer therapy development." (PMID 41309571, 2025). "Likewise CIP2A, β-catenin is also closely associated with cancer cell proliferation." (PMID 28521777, 2017).